UCP1 (uncoupling protein 1)
Diseases named in the same sentence as UCP1 in open-access papers (continued):
Sharing a sentence is not in itself a finding about the gene and the disease.
Obesity (continued). "Additionally, we find that metabolic effects of UCP1 may even be observable when no obesity is induced, in that case observable rather as the ability to retain body energy reserves based on a lowered energy intake." (PMID 30807213, 2019). "Importantly, we must note that some anti-obesity effects of PUFAs could be independent of UCP-1-dependent mitochondrial uncoupling." (PMID 31366145, 2019). "Although the mechanisms by which obesity inhibits UCP1 expression remain unclear, a role of inflammation has recently been proposed, since integrin alpha 4 (ITGA4)- and VCAM-1 mediated macrophage-adipocyte interactions were found to inhibit UCP1 expression by ERK1/2 and p38 pathway blockade." (PMID 30618796, 2018). "As UCP1 is capable of triggering a program of respiration and energy expenditure, the transdifferentiation of ADSCs into UCP1-expressing beige adipocytes might be another explanation that explicates the higher energy consumption in HFD-fed Pdcd4−/− mice as well as the resistance to obesity." (PMID 27031966, 2016). "While whole body JNK1 knockout results in resistance to diet induced obesity, adipocyte specific JNK1 knockout does not exhibit this phenotype, despite increased energy expenditure via classic UCP1 mediated thermogenesis." (PMID 40092442, 2025). "Finally, induction of UCP1 and improvement of thyroid hormone function at the level of adipose tissue using NAC could probably be a suitable strategy along with common treatments for obesity, i.e. diet therapy and increasing physical activity in reducing obesity-related disorders." (PMID 38702594, 2024). "In recent years, studies have shown that inactivation of uncoupling protein 1 (UCP1), the central element of heat production in BAT, did not potentiate diet-induced obesity, and also not require in long-term cold adaptation." (PMID 35282453, 2022). "However, PHA could not prevent obesity in UCP-1 KO mice induced by HFD." (PMID 33983894, 2021). "Upregulation of PGC-1α and UCP-1 in BAT induced by aerobic exercise for 8 weeks was observed in non-obese individuals, and also in obesity." (PMID 34677392, 2021). "The downregulation of UCP-1 was not improved, even though exercise histologically inhibited BAT whitening in obesity." (PMID 34677392, 2021). "Many studies have revealed no significant increase in levels of UCP1 and/or FGF21 (Fibroblast growth factor 21) in BAT, although the dose of n−3 PUFAs requisite for exerting an anti-obesity effect was increased threefold." (PMID 32595696, 2020). "We show here that even in thermally humanized and innately obesity-resistant 129S mice, the consumption of Western-style diets induces diet-induced thermogenesis mediated by UCP1 protein in BAT; in the absence of this, obesity develops." (PMID 30807213, 2019). "Although Ucp1 is normally expressed in BAT but not in WAT, several mouse mutants other than Ate1−/− that are resistant to diet-induced obesity have been shown to ectopically express Ucp1 in WAT." (PMID 19915679, 2009). "Notably, although most activation of BAT thermogenesis requires the help of Ucp1, endogenous FGF21 can prevent obesity by browning WAT in the absence of Ucp1 in mice." (PMID 36594101, 2023). "Our data support the theory coined by L. P. Kozak two decades ago that UCP1-independent thermogenesis could be activated, in an adaptive manner, in the absence of BAT and provide protection against both cold and obesity." (PMID 36720306, 2023). "In addition, in vivo studies on the absence of non-shivering (UCP1-dependent) thermogenesis should be performed to ensure if BAT and/or browning WAT are essential for the anti-obesity effects of these treatments." (PMID 36714578, 2022). "- Anti-obesity (↓body weight, eWAT, iWAT; ↓serum ALT, glucose, FFA, LDL-C; ↑energy expenditure) in HFD-mice (100, 200 mg/kg bw, p.o., 12 weeks). - Stimulated expression of UCP1 in wild-type adipocyte but not in Nrf2 knockout cells." (PMID 35769384, 2022).
Obesity (continued). "Induction of UCP1 expression in BAT may not be sufficient to build up robust resistance against fat deposits and obesity in instance of mitochondrial dysfunction." (PMID 32595696, 2020). "Indeed, a recent study has shown that water supplementation of 1.5% but not 1% succinate stimulates uncoupling protein 1 (UCP1)‐dependent thermogenesis from BAT, which induces robust protection against HFD‐induced obesity." (PMID 31318145, 2019). "In addition, although mice display increased Ucp1 mRNA expression in WAT and are resistant to high-fat diet (HFD)-induced obesity, they do not have an increased energy expenditure." (PMID 31708995, 2019). "However, in the concept of ‘browning’, a rising concept of approach in obesity care of which strategy is aimed to recruit functional brown adipocytes within WAT, CA failed to alter any thermogenic factors including UCP1 and PGC1α." (PMID 31443565, 2019). "Opposite to increasing the amount of BAT and UCP1 expression, having none, or reduced, BAT could also be a contributing factor in the development of obesity." (PMID 28481291, 2017). "Since UCP1 expression is a surrogate for BAT thermogenic activation, one interpretation is that in the high-Ca + NFDM mice enhanced BAT thermogenesis did not contribute to the anti-obesity effects of this diet." (PMID 22269778, 2012). "Uncoupling protein 1 (UCP1) in the inner mitochondrial membrane of BAT participates in the dissipation of the pH gradient generated by oxidative phosphorylation and the energy released as heat, there is a strong negative correlation between obesity and BAT amount." (PMID 36249777, 2022). "Ucp1, Ucp2, and Ucp3 expressed in BAT could generate heat after being activated by fatty acids and could play roles in nonshivering thermogenesis, diabetes, and obesity." (PMID 28665305, 2017). "Our data indicate that inhibition of COX activity increased weight gain and concomitantly attenuated diet-induced UCP1 expression in iWAT, but not iBAT in Sv129 mice kept at thermoneutrality, pointing to a novel role of COX activity in the control of energy balance and the development of obesity." (PMID 20613988, 2010).
Insulin resistance (94 papers, 2007 to 2026). Increased resistance towards insulin, that is, diminished effectiveness of insulin in reducing blood glucose levels. "A study in UCP1 knockout mice showed that loss of UCP1 increased susceptibility to Western-diet-induced insulin resistance and glucose intolerance." (PMID 35323702, 2022). "Inflammation causes insulin resistance in brown adipocytes and suppresses the induction of UCP-1 gene expression in BAT." (PMID 33799501, 2021). "Olanzapine induces insulin resistance (IR) by suppressing brown adipose tissue thermogenesis, damping expression of mitochondria uncoupling protein-1 and inhibiting glucose transporters, leading to impaired glucose uptake and decreased response to insulin." (PMID 40229885, 2025). "In mice, peripheral 5-HT alters both adipose and hepatic metabolism to induce insulin resistance and hepatic steatosis, while inhibiting UCP1 expression and uncoupled respiration in BAT, resulting in decreased systemic EE." (PMID 40455408, 2025). "GQD has been reported to improve HFD-induced insulin resistance, accompanied by increased expression of UCP1 and AMPKα in BAT." (PMID 35067163, 2022). "We found that the lipid biomarkers in UCP1 KI pigs had the highest correlations with lipid biomarkers in human insulin resistance and mice dysferlinopathy." (PMID 35096834, 2021). "In the present study, we provide evidence that Ptn deletion protects against the development of HFD-induced insulin resistance and liver steatosis, by increasing UCP-1 expression in BAT and inducing periovarian adipose tissue browning." (PMID 34502170, 2021). "BTS increased mRNA expression levels of leptin, adiponectin, and UCP1 in brown adipose tissue and improved insulin resistance in obese mice fed a high-fat diet." (PMID 28360931, 2017). "Increased Ucp1 and Pgc1a in exercised muscle of running mice suggests that a beige/brown fat phenotype develops, which differs from the fat phenotype that induces insulin resistance in high fat feeding." (PMID 27445983, 2016). "We wished to evaluate contributions of known UCP1 and UCP2 variants to metabolic traits in the Insulin Resistance and Atherosclerosis (IRAS) Family Study." (PMID 17397545, 2007). "Uncoupling protein 1 (UCP1) is inversely related to insulin resistance." (PMID 40149950, 2025). "Such localized inflammation impacts systemic metabolism through paracrine mechanisms; for instance, the pro-inflammatory cytokine IL-1β suppresses the expression of the thermogenic gene UCP1 in adipocytes, which reduces energy expenditure and exacerbates insulin resistance." (PMID 40568618, 2025). "Available evidence hypothesized that administration of NAC, a sulfur-containing antioxidant, may help weight loss in these individuals by regulating energy-related genes such as UCP1, as well as reducing insulin resistance and the anti-inflammatory pathway." (PMID 38702594, 2024). "When UCP-1 expression decreases, mitochondrial ROS increases, which may lead to insulin resistance in patients with type 2 diabetes." (PMID 35178098, 2022). "In fact, transcription of UCP1 was recognized in RA patients with unfavorable metabolic profile including overweight, insulin resistance and poor serum lipid profile suggesting that thermogenic conversion of energy was not enough to restore metabolic health in those patients." (PMID 34067093, 2021). "Exercise-induced secretion of irisin mediates the beneficial effects of exercise such as promoting adipocyte browning through uncoupling protein 1 (UCP-1), facilitating glycogen synthesis to improve insulin resistance, and promoting skeletal remodeling through the integrin receptor." (PMID 34943814, 2021). "Also, M1 macrophage induces insulin resistance through the production of pro-inflammatory cytokines and suppresses the induction of thermogenic adipocytes through inhibition of UCP-1 expression in obese adipose tissues." (PMID 32466447, 2020).
Insulin resistance (continued). "In the present study, we investigated the effects of BTS on the mRNA expression levels of UCP1, adiponectin, and leptin in adipose tissue, as well as insulin resistance, serum triglycerides, white adipocyte size, and white adipose tissue weight in high-fat diet-fed obese model mice." (PMID 28360931, 2017). "Similarly, knockdown of UCP1 in visceral fat also produced functional impacts on global metabolism impairment and insulin resistance." (PMID 28239649, 2017). "In contrast, BAT thermogenesis and UCP-1 expression could also be affected by diabetes and insulin resistance conditions." (PMID 25144367, 2014). "Furthermore, we found that α‐CD, which inhibits UCP1 activity, can improve iWAT and skeletal muscle functions and alleviate insulin resistance in aging mice, suggesting a potential therapeutic strategy against aging‐associated sarcopenia and insulin resistance." (PMID 39569747, 2025). "The inhibition of URAT1 in WAT by dotinurad induces the browning of WAT, and the inhibition of URAT1 in BAT increases the expression of UCP-1 and decreases the production of ROS, which may reduce body weight and visceral fat and may improve insulin resistance as well as glucose and lipid metabolism." (PMID 38474414, 2024). "In addition, administration of naringen into a diabetic 53-year-old African American female (a case study) showed that naringenin exerted its regulatory effects on insulin resistance and metabolic rate via activation of PPARα and PPARγ, leading to promotion of UCP1 and CPT1β." (PMID 36092543, 2022). "Also, the expression of GLUT4 and UCP1 in the insulin resistance group showed a significant decrease, which could be up-regulated by Gegen Qinliane Decoction treatment." (PMID 35067163, 2022). "However, the expression of UCP1 could be viewed as a protective mechanism developed to counteract insulin resistance and prevent development of classical metabolic syndrome in RA patients." (PMID 34067093, 2021). "Besides that, irisin increases the expression of uncoupling protein-1 (UCP-1), which is associated with the “browning” of subcutaneous white adipose tissue, induces an increase in energy expenditure, the improvement of insulin resistance, and possibly favors weight loss." (PMID 32443765, 2020). "UCP1 may play a major role in inducing insulin-resistance and diabetes in moderate-obese cases." (PMID 30458724, 2018). "Given the importance of UCP1 and UCP2 genes in metabolism, we chose to evaluate the five promoter or coding variants in these two genes previously associated with metabolic phenotypes (above) for associations in families from the Insulin Resistance and Atherosclerosis (IRAS) Family Study." (PMID 17397545, 2007). "Our findings demonstrate that UCP1 mRNA expression in human BAT is reduced with age, adiposity, hypertension, and insulin resistance, providing further evidence of a link between BAT and metabolic health in human adults." (PMID 38917410, 2024). "We previously demonstrated that deletion of CL synthase (CLS) driven by adiponectin-Cre, tamoxifen-inducible Rosa26-Cre, and tamoxifen-inducible UCP1-Cre (UCP1 Cre-ERT2) impairs thermogenesis and leads to insulin resistance." (PMID 36827367, 2023). "Although no significant impact of EPA on body weight and adiposity was observed, insulin resistance and inflammation were attenuated by EPA in both WT and UCP1 KO mice at both temperatures." (PMID 37240054, 2023). "Polyphenols play a significant role in reducing tissue insulin resistance and reducing visceral fat by participating in energy metabolism, altering gene expression (reducing PPAR-γ and increasing uncoupling protein 1)." (PMID 35538570, 2022). "The relatively high abundance of KEGG pathways predicted by Metascape were insulin resistance, cAMP, PPAR, and Apelin pathways, in which insulin resistance, PPAR signaling pathway, and Apelin signaling pathway contain AMPK/UCP1 pathway." (PMID 35962183, 2022).
Insulin resistance (continued). "In the present study, we show that Ptn deletion increases browning of periovarian white adipose tissue and UCP-1 expression in BAT and ameliorates HFD-induced insulin resistance and liver steatosis." (PMID 34502170, 2021). "To examine these findings, we also observed the expression of typical genes that are beneficial to improving insulin resistance, i.e., PGC-1α, PGC-1β, DIO2, UCP1, and PRARγ." (PMID 33705353, 2021). "Furthermore, they indicate that UCP1 KI pigs might be serve as a potential model for lipid metabolism-based explorations of the regulatory mechanisms of some metabolic disorders and myopathy in humans, especially insulin resistance and dysferlinopathy." (PMID 35096834, 2021). "WAT is essential for TG storage and insulin resistance, whereas brown adipose tissue (BAT) generates heat by dissipating energy via uncoupled respiration mediated by uncoupling protein 1 (UCP1)." (PMID 29535637, 2018). "For example, deletion of the transcriptional regulator Irf4 in Ucp1+ adipocytes disrupts the thermogenic gene program and exacerbates HFD-induced insulin resistance." (PMID 29861389, 2018). "TNF-α induces insulin resistance in BAT and directly inhibits the expression of uncoupling protein-1(UCP1) which is vital for the regulation of body temperature." (PMID 24236066, 2013). "The insulin tolerance test (ITT) showed that RvE1 alleviated the insulin resistance of mice fed the HFD which showed no significance in Ucp1−/− mice." (PMID 38933207, 2024). "WAT could be converted to beige adipose tissue (browning), which increases energy expenditure by activating the uncoupling protein 1 (UCP1), which improves systemic insulin resistance." (PMID 38474414, 2024). "Considering the potential role of NAC in ameliorating body adipose tissue, insulin resistance, and dyslipidemia, it is hypothesized that these beneficial effects of NAC may occur through increased UCP1 expression." (PMID 38702594, 2024). "Systemic administration of synthesized IMD reduced high-fat diet-induced body weight gain, as well as systemic insulin resistance, through activation of the AMP-activated protein kinase (AMPK) pathway and an increase of uncoupling protein 1 (UCP1) expression in adipose tissue." (PMID 37745233, 2023). "In previous studies, Ucp1−/− mice are not obese, and mice lacking PGC1α in adipose tissues develop insulin resistance without extra weight gain on HFD." (PMID 39872690, 2022). "In agreement with emerging evidence regarding the UCP1-independent role of beige fat18,19,36, fat-specific CUL2–APPBP2 blockade not only improved glucose intolerance, insulin resistance and lipid profile, but also suppressed WAT inflammation and fibrosis before changes in body weight." (PMID 35978186, 2022). "In agreement to that, phenolic compounds derived from coffee silverskin extract, including CA and CGA, prevented insulin resistance and improved lipid metabolism in murine adipocytes model via the insulin/PI3K/AKT pathway and elevated PGC-1α and UCP1 protein expression levels." (PMID 33371201, 2020). "Because fasting glucose and insulin levels did not change after G-CSF treatment, we also suggest that enhanced UCP-1 expression in BAT after G-CSF treatment is a process independent of insulin resistance." (PMID 25144367, 2014). "Moreover, the fasting serum insulin level was increased after chemerin treatment or Ucp1 gene ablation, even though the homeostasis model assessment of insulin resistance (HOMA-IR) showed a modest increase without a statistical difference." (PMID 38933207, 2024). "Moreover, retinol and RA are positive regulators of uncoupling protein 1 (UCP-1), and the overexpression of UCP-1 could improve skeletal muscle glucose transport and insulin resistance." (PMID 30800211, 2019).
Insulin resistance (continued). "WAT stores energy and releases cytokines and hormones that regulate insulin resistance and metabolism, while BAT consumes energy mainly through mitochondrial uncoupling in nonshivering thermogenesis mediated by Uncoupling protein-1 (UCP-1), as an adaption process to cold exposure." (PMID 30854010, 2019).